ARHGEF9 (Cdc42 guanine nucleotide exchange factor 9)
Description:
Acts as a guanine nucleotide exchange factor (GEF) for CDC42. Promotes formation of GPHN clusters (By similarity).
Synonyms: KIAA0424; PEM-2; COLLYBISTIN; DEE8; EIEE8; HPEM-2; PEM2
Tractability: PROTAC: ubiquitination databases record sites on it.
Gene: Protein-coding gene on chromosome X (63,634,967 to 63,809,274, reverse strand). Ensembl gene ENSG00000131089.
Subcellular location: Cytoplasm; Postsynaptic density
Subcellular location (Human Protein Atlas): Cytosol
Pathways (Reactome):
Signal Transduction: CDC42 GTPase cycle; G alpha (12/13) signalling events; NRAGE signals death through JNK; RHOQ GTPase cycle
Neuronal System: GABA receptor activation
Gene Ontology:
Molecular function: protein binding; guanyl-nucleotide exchange factor activity
Biological process: regulation of postsynaptic specialization assembly; regulation of small GTPase mediated signal transduction
Cellular component: cytosol; GABA-ergic synapse; postsynaptic density; postsynaptic specialization; cytoplasm
Gene-disease validity (ClinGen):
ClinGen rates the evidence that ARHGEF9 causes each of these diseases.
X-linked complex neurodevelopmental disorder (X-linked): Definitive. A complex neurodevelopmental disorder that is transmitted via X-linked inheritance, and is characterized by intellectual disability, autism and epilepsy.
Homologues: Orthologues: macaque ARHGEF9 (99% identical), mouse Arhgef9 (99% identical), pig ARHGEF9 (98% identical), guinea pig ARHGEF9 (97% identical), rat Arhgef9 (97% identical), chimpanzee ARHGEF9 (96% identical), tropical clawed frog arhgef9 (89% identical), dog ARHGEF9 (86% identical), zebrafish arhgef9b (83% identical). Paralogues in human: SPATA13 (60% identical), MCF2 (20% identical), TRIO (20% identical), KALRN (20% identical), MCF2L (20% identical), PLEKHG1 (19% identical), PLEKHG2 (19% identical), MCF2L2 (18% identical), PLEKHG4B (17% identical), VAV1 (17% identical), VAV2 (16% identical), PLEKHG4 (16% identical), and 10 more.
Diseases named in the same sentence as ARHGEF9 in open-access papers:
ARHGEF9 is named in the same sentence as 36 diseases in open-access papers, as found by Europe PMC text mining. Sharing a sentence is not in itself a finding about the gene and the disease. The quoted sentences say what the papers report.
epilepsy (11 papers, 2010 to 2024). A brain disorder characterized by episodes of abnormally increased neuronal discharge resulting in transient episodes of sensory or motor neurological dysfunction, or psychic dysfunction. "In a clinical setting, ARHGEF9-related syndromes have been associated with autism, developmental delays and speech impairment, with epilepsy being a common symptom in most cases." (PMID 37223033, 2023). "Mutations of ARHGEF9 have been associated with neurodevelopmental disorders, such as epilepsy, and autism in humans." (PMID 35664469, 2022). "By laser-microdissection, we investigated the impact of EAE on the alternative splicing of Arhgef9, a gene encoding a post-synaptic protein playing an essential role in GABAergic synapses and whose mutations have been related to CI and epilepsy." (PMID 36710925, 2022). "Epilepsy appears to be correlated with ID in ARHGEF9 mutation syndrome, being common among those individuals characterized by moderate to severe ID4." (PMID 35169261, 2022). "Epilepsy is noted in the majority of cases (63.4%) of the human ARHGEF9 mutation syndrome reported to date, and abnormalities in the baseline EEG (31.7%) are also commonly reported." (PMID 35169261, 2022). "Mutations in the ARHGEF9 gene are associated with intellectual disability and with numerous disorders including delayed motor development and epilepsy with facial dysmorphism." (PMID 36039362, 2022). "Accordingly, several mutations of the CB gene (ARHGEF9; Online Mendelian Inheritance in Man number: 300429) in patients have been implicated in epilepsy, X-linked intellectual disability, aggressive behavior, anxiety and, in one case, with hyperexplexia." (PMID 33901490, 2021). "The Gabra2–1 mutation demonstrates a striking parallel with the effects of ARHGEF9 mutation in human syndromes, whose symptoms include epilepsy, anxiety, mental retardation, aggressive behavior, sleep–wake cycle disruptions, early mortality, and hyperekplexia." (PMID 30087324, 2018). "To date, a relatively large number of different mutations in ARHGEF9 have been identified as causative in a seemingly heterogenous syndrome characterized not only by ID, but also a high incidence of epilepsy and a number of other features with varying presentation." (PMID 35169261, 2022). "In addition to the behavioral symptoms in ARHGEF9 mutation syndrome, there is a high incidence of epilepsy, and also relatively frequent reports of abnormalities in the baseline EEG." (PMID 35169261, 2022). "The importance of this protein has been further demonstrated by the identification of mutations in human CB gene (ARHGEF9, mapped at Xq11.1) in patients with diverse neurological abnormalities, including hyperekplexia, epilepsy, mental retardation, insomnia, aggressive behavior and anxiety." (PMID 20858277, 2010). "The first report on the linkage of ARHGEF9 with ASD identified a de novo microdeletion of Xq11.1 including entire ARHGEF9 in a male patient, who presented with severe intellectual disability (ID), epilepsy, and mild to moderate autism." (PMID 32244264, 2020).
Anxiety (7 papers, 2010 to 2024). Intense feelings of nervousness, tension, or panic often arise in response to interpersonal stresses. "The Cb knockout mouse has been reported to have impaired learning, convulsions, and also anxiety, drawing multiple parallels to human ARHGEF9 mutation." (PMID 35169261, 2022). "We also find phenotypes indicative of hyperactivity, anxiety, and impaired social interaction, all of which are reported with high prevalence in the ARHGEF9 mutation syndrome." (PMID 35169261, 2022). "The ArhGEF9, alternatively known as collybistin, works for Cdc42; and is associated with ID, epilepsy, anxiety, and aggression." (PMID 32858950, 2020). "In addition to ID, a number of other behavioral symptoms are reported as a part of the human ARHGEF9 mutation syndrome including hyperactivity, anxiety, and autism-like features." (PMID 35169261, 2022). "Gabra2-1 mice have deficits in working and recognition memory, as well as hyperactivity, anxiety, and reduced social preference, recapitulating the frequently reported features of ARHGEF9 patients." (PMID 35169261, 2022).
Intellectual disability (7 papers, 2018 to 2022). "In another diagnostic case-study, ONT-WGS was able to track down the exact breakpoints of a reciprocal translocation, which led to the identification of disrupted ARHGEF9 gene in a girl with intellectual disability." (PMID 31134132, 2019). "Specific RhoGEFs have been implicated in neurodevelopmental disorders, such as language impairment (ARHGEF19), intellectual disability (ARHGEF6, ARHGEF2), and moderate intellectual disability with speech delay (ARHGEF9)." (PMID 35959104, 2022).
hepatocellular carcinoma (4 papers, 2020 to 2024). A malignant tumor that arises from hepatocytes. "The ARHGEF9 gene is involved in the growth and development of cranial nerves and has been shown to play a role in inhibiting the growth of both hepatocellular carcinoma and gastric cancer cells." (PMID 39634181, 2024). "ARHGEF9 was reported to be DNA methylation biomarker for hepatocellular carcinoma." (PMID 36241648, 2022). "A previous study demonstrated that CHD1L upregulates the expression of ARHGEF9, which subsequently activates Cdc42, causing filopodia formation, epithelial-mesenchymal transition (EMT), and finally promotes hepatocellular carcinoma cell invasion and metastasis." (PMID 32922205, 2020). "ARHGEF9 has been shown to play a role in tumor cell migration, invasion and metastasis by linking oncogene CHD1L and Cdc42 pathway in hepatocellular carcinoma (HCC)." (PMID 32503434, 2020).
developmental delay (3 papers, 2020 to 2023). "Subsequently, more de novo deletions of ARHGEF9 were found in patients with ASD co-occurring with developmental delay (DD) or other mental disorders, suggesting that ARHGEF9 is a strong candidate for ASD." (PMID 32244264, 2020).
melanoma (2 papers, 2022 to 2025). A malignant, usually aggressive tumor composed of atypical, neoplastic melanocytes. "SOX3 is associated with tumor progression in liver cancer and ARHGEF9 promotes cytoskeleton variations that determine cell share in melanoma." (PMID 39416100, 2025). "Because filopodia mark the sites of future adhesion formation in WM266-4 melanoma cells, loss of ARHGEF9 filopodia could alter adhesion morphogenesis, resulting in morphogenesis defects on stiff 2D plastic and in 3D hydrogels." (PMID 36039362, 2022). "Depletion of ARHGEF9 was particularly effective at altering cell shape in melanoma cells on soft material." (PMID 36039362, 2022). "We propose that in melanoma cells, ARHGEF9 functions in a somewhat similar manner, where ARHGEF9 recruitment to the leading edge promotes actin reorganization into filopodia." (PMID 36039362, 2022). "We propose that melanoma cells utilize ARHGEF9 to promote filopodial-driven adhesion during morphogenesis in environments with varying rigidity and geometry." (PMID 36039362, 2022). "Taken together we show that ARHGEF9 promotes the formation of actin-rich filopodia, which serves to establish and stabilize adhesions and determine melanoma cell shape." (PMID 36039362, 2022). "ARHGEF9 is essential for filopodia formation, FAs assembly, and contractility in cells cultured on 2D materials, and for protrusion in melanoma cells embedded in 3D matrices." (PMID 36039362, 2022). "ARHGEF9 is required for melanoma cells to invade 3D matrices." (PMID 36039362, 2022). "ARHGEF9 may thus confer melanoma cells with the ability to invade diverse tissue during metastasis in a similar manner to how endothelial or neuronal cells migrate through the body during development." (PMID 36039362, 2022). "Thus, we conclude that ARHGEF9 is required for FAs morphogenesis in melanoma cells." (PMID 36039362, 2022). "Only two genes, ITSN2 and ARHGEF9, both of which are CDC42 GEFs, regulate melanoma shape on both soft and stiff materials." (PMID 36039362, 2022). "The reliance of WM266-4 cells on ARHGEF9 and CDC42 for the regulation of cell shape suggests that the activation of this pathway, either at the transcriptional or post-translational levels, represents a means by which melanoma tumor cells evolve the ability to metastasize." (PMID 36039362, 2022).
X-linked intellectual disability (2 papers, 2015 to 2019). An X-linked intellectual deficiency in which not enough information is known, reported or published to indicate whether a gene causes non-syndromic or syndromic presentations. "This process is disrupted by mutations in the collybistin gene (ARHGEF9), which cause X-linked intellectual disability (XLID) by a variety of mechanisms converging on disrupted gephyrin and GABAA receptor clustering at central synapses." (PMID 30914922, 2019).
Cognitive impairment (1 paper, 2024). Abnormal cognition is characterized by deficits in thinking, reasoning, or remembering. "ARHGEF9 is a potential candidate gene for X-linked hereditary diseases and cognitive impairment in cattle." (PMID 39682483, 2024).
cutaneous melanoma (1 paper, 2022). A primary melanoma arising from atypical melanocytes in the skin. "To determine if ARHGEF9 had a function in filopodial morphogenesis in other cell types, we inhibited ARHGEF9 in mouse cutaneous melanoma 21015 cells." (PMID 36039362, 2022).
Down syndrome (1 paper, 2022). "Of interest, sleep dysfunction is relatively consistently reported in patients with ARHGEF9 mutation, and has been identified as a component of a number of other types of syndromic ID including Down syndrome." (PMID 35169261, 2022).
dyslipidemia (1 paper, 2024). "Third, additional experiments are warranted to validate dyslipidemia as the link between AP and T2DM and to investigate the mechanisms of SLPI and ARHGEF9 in AP and T2DM and their relationship with dyslipidemia." (PMID 39634181, 2024).
Hypertension (1 paper, 2024). The presence of chronic increased pressure in the systemic arterial system. "Mechanistically, the miR‐193b‐3p/Arhgef9/apoptosis axis emerges as a key pathway linked to the neurogenic pathogenesis of hypertension." (PMID 38934856, 2024). "Furthermore, the effects caused by miR‐193b‐3p and Arhgef9 on neuronal apoptosis and hypertension progression were disclosed." (PMID 38934856, 2024). "miR‐193b‐3p suppressed the progression of hypertension by decreasing RVLM neuronal apoptosis, and the underlying mechanism was that miR‐193b‐3p negatively regulated Arhgef9 expression." (PMID 38934856, 2024). "miR‐193b‐3p and miR‐346 are newly identified factors in RVLM that hinder hypertension progression, and the miR‐193b‐3p/Arhgef9/apoptosis pathway presents a potential mechanism, highlighting the potential of targeting miRNAs for hypertension prevention." (PMID 38934856, 2024). "Most notably, this research substantiated the regulatory role of miR‐193b‐3p in inhibiting RVLM neuronal apoptosis through targeted suppression of Arhgef9, resulting in a decrease in neuronal excitability and sympathetic outflow and consequently impeding the development of hypertension." (PMID 38934856, 2024). "Whether the miR‐193b‐3p/Arhgef9/neuronal apoptosis axis in RVLM is involved in the neurogenic pathogenesis of hypertension was unveiled." (PMID 38934856, 2024).
obstructive sleep apnea (1 paper, 2022). "Patients with ARHGEF9 mutation are reported to have disrupted sleep-wake cycle, spike-wave discharges during slow wave sleep, as well as NREM parasomnias, and obstructive sleep apnea." (PMID 35169261, 2022).
tumor (6 papers, 2015 to 2025). "The Cdc42-specific GEF ARHGEF9 is up-regulated by the oncogene transcription factor CHD1L and has been previously implicated in tumor cell migration, invasion and metastasis by increasing cell motility and inducing filopodia formation." (PMID 26633832, 2015). "CHD1L can contribute to tumor cell migration, invasion, and metastasis by increasing cell motility and inducing filopodia formation and EMT via ARHGEF9-mediated Cdc42 activation in HCC." (PMID 26599012, 2015).
cancer (2 papers, 2012 to 2020). A tumor composed of atypical neoplastic, often pleomorphic cells that invade other tissues. "Although the splicing events of these genes were not reported previously, their gene expression level was linked to tumorigenesis or prognosis of CRC (SERPINA1) or other cancer types (ARHGEF9, CHEK1, HKDC1)." (PMID 32503434, 2020). "The other genes (SMARCE1, DISC1, CENTD2, RHOT1, ARHGAP6, ARHGEF9 and ARHGEF11) are also involved in cancer progression or chemoresistance." (PMID 23300757, 2012).
neurodevelopmental disorder (2 papers, 2018 to 2022). A behavioral and cognitive disorder with onset during the developmental period that involves impaired or aberrant development of intellectual, motor, or social functions. "The mechanism by which mutations of ARHGEF9 lead to neurodevelopmental disorder is beginning to be clarified; as CB is involved in the formation of inhibitory GABAergic synapses, the loss-of-function mutations of ARHGEF9 lead to neuronal hyperexcitability." (PMID 29925821, 2018).
ARHGEF9 also shares sentences with these, for which no sentence is quoted: autism (4 papers); hyperekplexia (3); infantile epileptic encephalopathy (2); intellectual disability syndrome (2); mental disorder (2); colon adenocarcinoma (1); Epileptic encephalopathy (1); familial hemiplegic migraine (1); gastric cancer (1); glioma (1); liver cancer (1); lung adenocarcinoma (1); multiple sclerosis (1); myopia (1); neuronal migration disorders (1); Parasomnia (1); rectum adenocarcinoma (1); speech delay (1); speech disorder (1); startle disease (1).